SYT10 (synaptotagmin 10)
Description:
Ca(2+) sensor specifically required for the Ca(2+)-dependent exocytosis of secretory vesicles containing IGF1 in neurons of the olfactory bulb. Exocytosis of IGF1 is required for sensory perception of smell. Not involved in Ca(2+)-dependent synaptic vesicle exocytosis (By similarity). Acts through Ca(2+) and phospholipid binding to the C2 domain: Ca(2+) induces binding of the C2-domains to phospholipid membranes and to assembled SNARE-complexes; both actions contribute to triggering exocytosis (By similarity).
Tractability: Antibody: UniProt predicts a signal peptide or a membrane-spanning region; its Gene Ontology location is reachable by antibodies, with medium confidence.
Gene: Protein-coding gene on chromosome 12 (33,374,238 to 33,439,819, reverse strand). Ensembl gene ENSG00000110975.
Subcellular location: Cytoplasmic vesicle, secretory vesicle membrane
Subcellular location (Human Protein Atlas): Nucleoplasm; Vesicles
Pathways (Reactome):
Gene expression (Transcription): NPAS4 regulates expression of target genes
Neuronal System: Neurexins and neuroligins
Gene Ontology:
Molecular function: calcium ion binding; calcium ion sensor activity; calcium-dependent phospholipid binding; SNARE binding; identical protein binding; phosphatidylinositol-4,5-bisphosphate binding; phosphatidylserine binding; protein heterodimerization activity; protein homodimerization activity
Biological process: chemical synaptic transmission; positive regulation of calcium ion-dependent exocytosis; regulation of calcium ion-dependent exocytosis; sensory perception of smell; synaptic vesicle exocytosis; vesicle-mediated transport
Cellular component: exocytic vesicle; plasma membrane; glutamatergic synapse; membrane; presynapse; transport vesicle membrane
Genetic constraint (gnomAD): Loss-of-function variants: 31 observed, 51.41 expected, observed/expected ratio (o/e) 0.6, 90% interval 0.45 to 0.81. The upper end of that interval is the gene's LOEUF score, 0.81, which puts it in group 3 of 6, group 1 being the genes least tolerant of losing a copy. Missense variants: 603 observed, 664.5 expected, observed/expected ratio (o/e) 0.91, 90% interval 0.85 to 0.97. Synonymous variants: 233 observed, 238.08 expected, observed/expected ratio (o/e) 0.98, 90% interval 0.88 to 1.09.
Homologues: Orthologues: chimpanzee SYT10 (99% identical), macaque SYT10 (98% identical), pig SYT10 (97% identical), guinea pig SYT10 (93% identical), rat Syt10 (93% identical), mouse Syt10 (93% identical), dog SYT10 (92% identical), tropical clawed frog syt10 (85% identical), rabbit SYT10 (84% identical), zebrafish syt10 (75% identical). Paralogues in human: SYT6 (63% identical), SYT9 (56% identical), SYT3 (49% identical), SYT1 (31% identical), SYT2 (29% identical), SYT11 (28% identical), SYT7 (28% identical), SYT17 (27% identical), SYT5 (27% identical), SYT4 (26% identical), RPH3A (23% identical), SYT12 (23% identical), and 19 more.
Diseases named in the same sentence as SYT10 in open-access papers:
SYT10 is named in the same sentence as 6 diseases in open-access papers, as found by Europe PMC text mining. Sharing a sentence is not in itself a finding about the gene and the disease. The quoted sentences say what the papers report.
Arrhythmia (2 papers, 2020 to 2023). Any cardiac rhythm other than the normal sinus rhythm. "Bmal1 expression was reduced by 65% in heterozygous Syt10-Cre mice (Syt10-Cre+/−; Bmal1loxp/loxp), which did not result in circadian arrhythmia, whereas Bmal1 transcript levels decreased by 83% in homozygous Syt10-Cre mice (Syt10-Cre+/+; Bmal1loxp/loxp) that was accompanied by arrhythmia." (PMID 36593479, 2023).
atrial fibrillation (2 papers, 2019 to 2020). A disorder characterized by an electrocardiographic finding of a supraventricular arrhythmia characterized by the replacement of consistent P waves by rapid oscillations or fibrillatory waves that vary in size, shape and timing and are accompanied by an irregular ventricular response. "SNAP25, a proposed interaction partner of SYT10, is the target of botulinum toxin A. Injection of botulinum toxin A into the neural ganglia of CAD/atrial fibrillation patients was recently shown to reduce the occurrence of post-operational atrial fibrillation." (PMID 32678143, 2020).
neurodevelopmental disorder (1 paper, 2025). A behavioral and cognitive disorder with onset during the developmental period that involves impaired or aberrant development of intellectual, motor, or social functions. "The SYT10/IGF-1 signaling pathway may play a potential key role in Pb-induced neurodevelopmental disorders." (PMID 40559938, 2025).
SYT10 also shares sentences with these, for which no sentence is quoted: Brugada syndrome (1 paper); coronary artery disease (1); Parkinson disease (1).